IL10 (interleukin 10)
Diseases named in the same sentence as IL10 in open-access papers (continued):
Sharing a sentence is not in itself a finding about the gene and the disease.
lung carcinoma (continued). "The results demonstrate that administration with miR-98-laden liposomes can inhibit lung cancer growth in mice via suppression of IL-10 expression in B cells." (PMID 27605397, 2016). "Similar results were obtained using lung cancer model in that chronic COX-2 inhibition reduced antigen presenting cell mediated IL-10 secretion but enhanced IL-12 secretion in the tumor microenvironment and consequently reduced tumor size." (PMID 25680189, 2015). "Although the mechanism of the involvement of CIP2A in lung cancer is not clearly understood, some recent studies have indicated the involvement of interleukin-10 (IL-10) in this event." (PMID 25015035, 2014). "A number of pro- and/or anti-inflammatory cytokines have been described as possessing dual roles in lung cancer including TNFα, IL-6, IL-8, IL-10, VEGF, and PDGF." (PMID 26316944, 2014). "Of the tumors of the 385 lung cancer patients, 241 were available for evaluation of IL-10 mRNA expression levels." (PMID 22848356, 2012). "Previous reports have shown that IL-10 has different prognostic significance in early- and late-stage lung cancer patients." (PMID 22848356, 2012). "Since then, numerous attempts have been made to find out the exact role that IL-10 has to play in the prognosis of Lung cancer." (PMID 23034167, 2012). "This review updates current understandings on the effect of the cytokines TGF-β, IL-10, and IL-17A on the lung immune responses to antigen, and analyzes their involvement in allergic asthma and lung cancer." (PMID 22855687, 2012). "In the case of MNCs from lung cancer patients, IL-10 production was more prominent when cells were incubated with IL-2 than with IL-15." (PMID 9744501, 1998). "Enriched tumor markers, inflammatory imbalance, particularly the IL-6/IL-10 ratio, enhanced ctDNA detection, and local immunosuppressive immune features support the utility of BALF as a minimally invasive liquid biopsy for lung cancer evaluation and risk stratification." (PMID 41970393, 2026). "In addition, miRNA-98 is an important miRNA that is associated with IL-10 in multimorbidity, such as HCC, lung cancer, and myocarditis." (PMID 41300695, 2025). "Moreover, the upregulation of IL-10 expression in TAMs has been reported to contribute to lung cancer immunosuppression and cancer progression." (PMID 40710006, 2025). "As an important factor for poor prognosis, the primary effect of IL-10 on lung cancer cells may be to increase their metastatic potential by promoting angiogenesis and resistance to apoptosis." (PMID 38459564, 2024). "Additionally, IL-10 expression in the plasma of patients with lung cancer was higher than that in normal participants." (PMID 38521953, 2024). "The levels of IL-10 in the lung cancer mice were elevated, which may be due to the autoimmune defense generated by the tumor." (PMID 39594117, 2024). "For AAs, optimal lung cancer prediction was achieved using IL-8, IL-10, and MCP-1." (PMID 38276239, 2024). "Notably, IL-10 and MCP-1 displayed significant increases specifically in AA lung cancer patients, with MCP-1 levels associated with lung adenocarcinoma cases." (PMID 38276239, 2024). "MCP-1 and IL-10 levels were specifically elevated in AA lung cancer patients." (PMID 38791954, 2024). "Male lung cancer patients have higher blood IL-10 levels than females." (PMID 39003443, 2024). "Additionally, conditioned media from MUFA-treated lung cancer cells had little apparent effect on the release of IL-10, M-CSF, and IL-6 from monocytes, which suggest that MUFA does not lead to a complete shift in the cytokine profile." (PMID 39100092, 2024). "In summary, HIIT may bidirectionally regulate TAM polarization and improve the immune microenvironment of lung cancer by modulating IL-10, IL-12, CD47, and CD24." (PMID 37691942, 2023).
lung carcinoma (continued). "Ten blood cytokine levels, including; granulocyte-macrophage colony-stimulating factor, TNF (alpha), and IFN (gamma), IL1, IL6, IL12, IL4, IL8, IL10, IL5, were compared between 296 European-Americans and 170 African-Americans to determine their associations with lung cancer." (PMID 36874133, 2023). "Animal studies demonstrated that aerobic exercise could reduce lung cancer inflammation, increase the levels of the anti-inflammatory cytokine IL-10, and decrease the levels of pro-inflammatory cytokines (such as TNF-α, IL-6, and IL-1)." (PMID 37691942, 2023). "Notably, elevated serum levels of IL-1β, IL-10, and TNF-α were linked to lung cancer risk only in the African American population." (PMID 38067398, 2023). "Moreover, the ROC plot analysis revealed that several inflammatory markers, including IL-1b, IL-2, IL-6, IL-10, IL-12p70, and TNF-alpha, are significantly associated with the risk of lung cancer." (PMID 37373957, 2023). "Notably, elevated levels of IL-1β, IL-10, and TNF-α were linked to lung cancer risk only in the African American population." (PMID 38067398, 2023). "Additionally, endurance exercise downregulates TNF-α and iNOS expression in lung cancer tissue but upregulates IL-6 and IL-10 expression." (PMID 37691942, 2023). "In this study, we found that endurance exercise can reduce the proportion of M1-type TAMs in lung cancer tissues, while HIIT antagonistically regulates M1 and M2 polarization of TAMs by increasing the levels of IL-10 and IL-12 in lung cancer tissues and circulating IFN-γ." (PMID 36186906, 2022). "Both TGF-β and IL-10 are essential factors that promote lung cancer cell migration." (PMID 35158999, 2022). "Using the CRISPR-ELISA assay to profile plasma cytokines in 127 lung cancer patients and 125 cancer-free smokers, we develop a panel of plasma cytokine biomarkers (IL-6, IL-8, and IL-10) for early detection of the disease, with 80.6% sensitivity and 82.0% specificity." (PMID 36498497, 2022). "When compared to exosomes of HEK 293T cells (a human embryonic kidney cell line), the concentration levels of TGF-β and IL-10 were increased in exosomes of the two human lung cancer cell lines, particularly in exosomes from cells cultured under hypoxic conditions." (PMID 35158999, 2022). "Lung cancer cell lines secrete IL-6, IL-10 and TGFβ, which are also found in pleural effusions." (PMID 33466674, 2021). "Besides, (-)-Guaiol, which is an effective constituent of the Fuzheng Quxie Formula, inhibited the EMT process of lung cancer by targeting M2 macrophages, and IL-10/STAT3 pathway is involved in the regulation of signaling pathway." (PMID 34475962, 2021). "TAM- (M2-) based IL-10 presented constant prognostic prominence in lung cancer patients." (PMID 34336101, 2021). "TAM-based IL-10 tends to endorse the stemness of lung cancer." (PMID 34336101, 2021). "Higher IL-6, IL-8, and IL-11 levels were found to be associated with worse survival in patients with cancer, whereas elevated IL-10 and IL-6 levels might be markers of a favorable prognosis for colorectal cancer and lung cancer, respectively." (PMID 33912192, 2021). "Additionally, TAM-derived IL10 promotes the stemness of lung cancer via JAK1/STAT1/NFKB/NOTCH1 signaling pathways in vivo tumorigenesis mouse models." (PMID 32219066, 2020). "Evidences indicate that increase of IL-6 was not only occurred in liver ablation, researches focus on lung cancer, including primary lung cancer and pulmonary metastases demonstrated that serum IL-8, IL-1β, IL-6, IL-10, IL-12 and TNF-α were significantly raised after radiofrequency thermal ablation." (PMID 32847533, 2020). "TAMs-derived IL10 perform several tasks in lung cancer progression and development." (PMID 32219066, 2020). "In addition, miRNA-98 is an important miRNA, which is associated with IL-10 in various diseases, such as HCC, Lung cancer, Myocarditis, etc.." (PMID 32582189, 2020).
lung carcinoma (continued). "To conclude, the future design of novel lung cancer therapies should consider polarization of macrophage to M1 phenotype through exogenous upregulation of miR-155 or miR-1207-5p, suppression of miR-21, or miR-103a, inhibition of IL-10 and agonist of CD47." (PMID 32477352, 2020). "Post-HLA class Ia downregulation and HLA class Ib upregulation, an increase in IL-10 production, could be traced in lung cancer." (PMID 29602958, 2018). "Current literature suggests that the secretion of cytokines IL-10 and IFNγ from TAMs can up-regulate B7x on lung cancer and hematological malignancies like Non-Hodgkin Lymphoma (NHL), however our studies did not confirm this after assaying several different human and murine tumors." (PMID 29137299, 2017). "Some of the significant associations found in the previous studies were not validated in our meta-analysis, for example, IL-10 -1082A/G polymorphism was associated with an increased lung cancer risk." (PMID 28977953, 2017). "In this study, we not only confirmed the upregulation of IL10 and demonstrate its correlation with poor lung cancer prognoses but also showed that knocking out IL10 in two spontaneously induced lung cancer mice, Kras4bG12D and EGFRL858R, dramatically prevented lung cancer development in vivo." (PMID 26956044, 2016). "We assessed whether STAT3 is responsible for IL-10 upregulation in lung cancer-conditioned DCs and if it is a target for laricitrin." (PMID 27833081, 2016). "In conclusion, these results indicate that TREM-2 might act as a negative immuno-regulatory molecule through Syk pathway in an IL-10 dependent manner and partially predicts prognosis in lung cancer patients." (PMID 27102437, 2016). "In conclusion, we have shown that TREM-2 might act as a negative immuno-regulatory molecule through Syk pathway in an IL-10 dependent manner, and partially predict prognosis in patients with lung cancer." (PMID 27102437, 2016). "In conclusion, up regulation of miR-98 inhibits the expression of IL-10 in B cells, which may contribute to inhibit the lung cancer tolerance in the body." (PMID 27605397, 2016). "Based on the information above, we hypothesize that the impairment of miR-98 expression results in the over expression of IL-10 in B cells in patients with lung cancer." (PMID 27605397, 2016). "In addition, because IL10 is a secreted protein, we studied the IL10 levels in the sera of 60 normal individuals and 60 lung cancer patients." (PMID 26956044, 2016). "Finally, we analyzed the relationship between phospho-Src (Y419) and the survival rate of 102 lung cancer patients with positive IL10 expression." (PMID 26956044, 2016). "This study test a hypothesis that miR-98 suppresses the expression of IL-10 in B cells of subjects with lung cancer." (PMID 27605397, 2016). "In addition, shorter survival times have been reported in advanced lung cancer patients who had high serum IL-10 levels, when compared with similar patients who had low serum IL-10 levels." (PMID 22848356, 2012). "Besides that, IL-10 is also known to be produced and secreted by different types of cancer cells, including lung cancer." (PMID 22855687, 2012). "Promotion of lung cancer cell invasion by IL-10 was also reported previously." (PMID 23118878, 2012). "Consequently, the apoptosis of both lung cancer cell types was decreased by treatment with IL-10 and increased by IL-10 neutralized antibody." (PMID 22848356, 2012). "Despite these contradictions, the immune-suppressive molecule IL-10 is an important factor during the induction of airway tolerance and might be a promising target for future approaches to lung cancer therapy." (PMID 22855687, 2012). "IL-10 is a potent immunosuppressive factor that may promote lung cancer growth by suppressing macrophage function and enabling tumors to evade immunosurveillance." (PMID 21595995, 2011).
lung carcinoma (continued). "Additionally, several inflammatory chemokines and interleukins (ILs), including IL-6, IL-8, and IL-10, involved in perioperative immune modulation, may help predict complications following lung cancer surgery." (PMID 41228236, 2025). "Statistical significance was observed for IL-1b (p = 0.044), IL-2 (p = 0.040), IL-6 (p = 0.001), IL-10 (p = 0.008), IL-12p70 (p = 0.001), and TNF-alpha (p = 0.046), indicating that these inflammatory markers are significantly associated with the risk of lung cancer." (PMID 37373957, 2023). "Of note, we found greater levels of inflammatory factors such as IL‐4, IL‐10 and TGF‐β were associated with a higher CYP2E1 level in peritumoral tissues, indicating that CYP2E1 may be related to the inflammation response in lung cancer." (PMID 37875398, 2023). "Finally, focusing on the role of tumor microenvironment in c-Src/EGFR regulation, Interleukin 10 (IL10) has been proposed as a cooperative agent in the oncogenic progression of lung cancer by increasing phosphorylation levels of EGFR and c-Src in a dose-dependent manner." (PMID 32517369, 2020). "Furthermore, we isolated F4/80+ TAMs from PBS- or HCQ-treated mice with orthotopic lung cancer, and we found that the M1-like molecules (Nos2, Ifng, IL12b,and IL1b) were up-regulated and the M2-like molecules (Arg1, Tgfb1, IL10, and Ido1) were down-regulated with HCQ treatment." (PMID 30373678, 2018). "In addition to being produced by tumor cells, the increased alveolar macrophages IL-10 production induced by NNK may favor the development of lung cancer." (PMID 29732034, 2018). "Moreover, IL10 levels were significantly increased in the lungs and serum of EGFRL858R- and Kras4bG12D-induced lung cancer mice, indicating that IL10 might facilitate lung cancer tumorigenesis." (PMID 26956044, 2016). "Inhibition of antitumour function via secretion of the anti-inflammatory cytokine IL-10 as well as reduced secretion of proinflammatory cytokines and reduction of mannose receptor expression on alveolar macrophages may contribute to lung cancer progression and metastasis." (PMID 26316944, 2014). "Therefore, it is necessary to further define the role of IL-10 in lung cancer." (PMID 22855687, 2012). "Thus, some preclinical and clinical studies suggest that IL-10 might be important for tumor rejection, meaning that the role of IL-10 for lung cancer still needs to be elucidated." (PMID 22855687, 2012). "In lung cancer, transforming growth factor beta (TGF-β), IL-10, cytokines, and chemokines released by M2 macrophages can promote tumor growth and infiltration." (PMID 39963673, 2025). "Parallel observations from Chinese lung cancer cohorts included enriched TNF-α pathway activity and higher plasma TNF levels, while elevated IL-10/CCL2 in elderly patients and ST6GAL1 in high-grade irAEs further highlight shared inflammatory axes." (PMID 40722787, 2025). "This proposed strategy is further supported by earlier findings that demonstrated the in vitro synergy between IL-10 and IL-2 in expanding and enhancing the activity of CD8+ T cells derived from lung cancer patients." (PMID 40149345, 2025). "Matrine, a naturally occurring alkaloid found in Sophora flavescens, reduces IL-10, Arg-1, and CD206 in TAMs in lung cancer models." (PMID 40723226, 2025). "Pleural effusions from lung cancer often show significantly elevated levels of CD4+T lymphocytes, which are the primary source of IL-10 production." (PMID 39003443, 2024). "Depletion of the IL-37 gene in two distinct lung cancer cell lines (H460 and A549) suppressed MARCO expression and diminished IL-10 production in co-cultured macrophages." (PMID 38983267, 2024). "Combining recombinant mouse IL-10 protein and PD-1 blocking can optimize the anti-PD-1/L1 therapeutic effect of EGFRL858R mutant lung cancer." (PMID 39188712, 2024). "Among AAs, the biomarker panel, composed of IL-8, IL-10, and MCP-1, achieved a sensitivity of 75% and a specificity of 79% for lung cancer detection." (PMID 38276239, 2024).
lung carcinoma (continued). "The research by Vahl and colleagues showed that IL-10 competes with IFN-γ on the PD1/PDL1 pathway, potentially contributing to resistance to PD1/PDL1 immunotherapy in lung cancer patients." (PMID 36874011, 2023). "The study measured the concentration of IFN-γ, TNF-α, IL-1β, IL-2, IL-4, IL-6, IL-10, and IL-12p70, in venous blood and BALF of a total of 33 patients with lung cancer and 33 patients with benign lung diseases." (PMID 37373987, 2023). "Tlr9 activates inflammatory factors such as il-1 and il-8, increasing immune inhibitory factor il-10 secretion and MMP-2 expression to enhance the invasion and metastasis of lung cancer cells." (PMID 36991462, 2023). "The level of Th17-related cytokine (IL-17) was augmented and the levels of Treg-related cytokines (IL-10, TGF-β) were diminished in the peripheral blood of propofol-anesthetized elderly lung cancer patients after operation (all p < 0.01)." (PMID 36434505, 2022). "IL-10 and IL-10 receptors were found in lung cancer tissue from NSCLC patients and lung cancer cell line cultures." (PMID 36140220, 2022). "Of the 12 cytokines, six (IL-6, IL-8, IL-10, IL-12p70, IFN-γ, and TNF-α) displayed a higher level in plasma of lung cancer patients compared with cancer-free smokers (All p < 0.001)." (PMID 36498497, 2022). "Compared with X-rays, carbon ions increased the exposure of high mobility group box 1 (HMGB1) while relatively reduced the exposure levels of immunosuppressive factors IL-10 and TGF-β in lung cancer cell lines." (PMID 36348363, 2022). "MPE-Mφ showed relatively higher expression levels of M1 (IL-1β, IL-6, and CXCL10), M2 (CCL18 and IL-10), and pan-macrophage markers (CSF1 and PTPRC) compared to MDMs from lung cancer patients or HCs." (PMID 33175182, 2021). "In terms of the simple regulation of lung cancer migration, studies have confirmed that transcripts of TGF-β, lnc-MMP2-2, IL-10, as well as those of other genes in exosomes derived from lung cancer cells have regulatory functions." (PMID 34511114, 2021). "Exosomes of lung cancer cells released of TGF-β and IL-10 into the tumor microenvironment, which improved the migration ability and promoted metastasis in lung cancer cells." (PMID 33999859, 2021). "The manifestation of an assemblage of IL-6 and IL-10 or CCR-2, CCL-2 connects to a shoddy projection in patients with lung cancer." (PMID 34336101, 2021). "In lung cancer, activated ERK1/2 signaling promoted the secretion of IL-10 and recruited immunosuppressive Tregs and M2 polarized tumor-associated macrophages to the tumor microenvironment." (PMID 32821247, 2020). "Significantly elevated expression of IL1-β, IL-6, IL-8, IL-10, IL-17, TNF-α, TGF-β, IFN-γ, and C-X-C motif chemokine ligand 1 (CXCL1) has been seen in colorectal cancer and other solid cancers like lung cancer." (PMID 32425932, 2020). "That study detected the contents of such plasma cytokines as IL-1, IL-6, IL-10, tumor necrosis factor α (TNF-α), and TGF-β1 in 34 lung cancer patients at different time points and found the incidence of SRP as 23.5%." (PMID 29147071, 2017). "MSCs significantly augmented lung cancer metastasis, attenuate concentrations of proinflammatory cytokines (TNF-α, IL-17), and increase levels of immunosuppressive IL-10, nitric oxide, and kynurenine in sera of LLC1-treated mice." (PMID 28798777, 2017). "In mouse primary lung cells, EGF increased the expression and secretion of IL10, and in the EGF-treated lung cancer cells, IL10 secretion was also increased." (PMID 26956044, 2016). "Therefore, we attempted to investigate whether IL10 affects lung cancer development in vivo." (PMID 26956044, 2016). "Some of these cytokines (IL-6, IL-8, IL-10, IL-22, VEGF, TGF-β, and TNF-α) have also been studied to determine their role in lung cancer and are described in comparison to other cytokines next." (PMID 27445423, 2016). "In conclusion, IL10 and EGFR regulate each other through positive feedback, which leads to lung cancer formation." (PMID 26956044, 2016).